CXCL10 (C-X-C motif chemokine ligand 10)
Diseases named in the same sentence as CXCL10 in open-access papers (continued):
Sharing a sentence is not in itself a finding about the gene and the disease.
infection (continued). "Cytokine signaling of IL-1β, IL-23, IL-17A, CCL7, CXCL10, TRAIL, CD40L, and BAFF provides protection against acute WNV infection in mice; IL-10 and IL-22 aid in WNV pathogenicity; IL-6 and IL-12 had no apparent effect during infection; and CCL2, TNF-α, and FasL roles remain elusive." (PMID 36992514, 2023). "Moreover, infection with lethal strains of SARS-CoV demonstrated worse lung pathology and higher levels of induction of inflammatory chemokines, such as Cxcl10 and Ccl2, than infection with non-lethal SARS-CoV strains that replicated to similar or even higher levels in the lung." (PMID 33613280, 2020).
cancer (633 papers, 2007 to 2026). A tumor composed of atypical neoplastic, often pleomorphic cells that invade other tissues. "Transcriptomic analyses revealed that MTAP-deficient cancer cells reprogram immune signaling pathways and suppress the expression of CXCL10, a key chemokine for T cell recruitment, thereby contributing to a non-inflamed, “cold” TME." (PMID 41246302, 2025). "Cxcl10 and Cxcl11 are chemokines implicated not only in immune disorders but also in cancer progression and T cell-mediated immune responses." (PMID 41019339, 2025). "One mutant allele in CXCL10 A-1447G polymorphism (AG) increased the chance of cancer (OR = 4.902, 95% CI = 2.70–8.87) and two mutant alleles (GG) increased more (OR = 7.174, 95% CI = 2.48–20.68)." (PMID 39359425, 2024). "Recent studies have linked CXCL10 to the progression of various cancers, including pancreatic, breast, ovarian, and colorectal cancer." (PMID 38461458, 2024). "One mutant allele in CXCL10 A-1447G polymorphism increased the chance of cancer (OR = 4.902, 95% CI = 2.70–8.87, P < 0.001) and two mutant alleles increased more (OR = 7.174, 95% CI = 2.48–20.68, P < 0.001)." (PMID 39359425, 2024). "CXCL1, CXCL5, and CXCL10 have generally been considered to be pro-tumorigenic in several cancer types, as they are associated with poorer prognosis and an immunosuppressive microenvironment." (PMID 39623404, 2024). "CXCL10 is linked to various diseases, including cancer, and infectious diseases, making it a potential therapeutic target." (PMID 39749215, 2024). "Cxcr3 and its ligands are associated with a T cell inflamed signature in many cancers and plasma levels of Cxcl9 and Cxcl10 are associated with prolonged survival in PDA patients treated with chemotherapy." (PMID 36472588, 2023). "Taken together, the results indicate the crucial role of CCL5 and CXCL10 in mediating T cell recruitment in RB1-deficient cancer cells." (PMID 37937640, 2023). "Cxcr3 is expressed on a subset of Foxp3 + regulatory T cells (Treg) and Cxcl10 expression by cancer-associated fibroblasts can recruit suppressive Treg." (PMID 36472588, 2023). "In an orthotopic PDAC animal model known to develop cancer-associated pain, administration of CXCL10- or CCL21-neutralizing antibodies significantly reduced the extent of nerve fiber hypertrophy and, consequently, the development of cancer-associated pain." (PMID 37834436, 2023). "Consistent with previous findings, we demonstrated that T cell modulators, IL15 and CXCL10, are often deleted in cancers, and these deletion events coincide with TLS loss in tumors." (PMID 37348499, 2023). "During the course of cancer therapy, a high change rate of IL‐6, IL‐8, CXCL10, CCR1, and CCL5 was significantly associated with poor PFS." (PMID 37062076, 2023). "Pan-cancer analysis independently verified the prevalence of CXCL10 upregulation in other cancers with viral or bacterial association." (PMID 35433690, 2022). "CXCL10 expression was associated with increased cancer cell resistance to LDK-378, brigatinib, alectinib, and PF-06463922, among others." (PMID 35982458, 2022). "The concomitant release of the neutrophil chemoattractants CXCL1, CCL2 and CXCL10 by murine cancer cells is a shared hallmark of the stress program elicited by photodynamic therapy (PDT) and mitoxantrone but not accidental necrosis or tolerogenic apoptosis." (PMID 36139473, 2022). "As for the chemokine molecules, studies support that CXCL10 is associated with exacerbating inflammation and also plays a role in the pathological process of cancers." (PMID 36239108, 2022). "In contrast, others have shown an association between CXCL10 levels and cancer cell aggressiveness, gemcitabine resistance and worse survival." (PMID 35954489, 2022). "In lung cancer models mutated for KRAS, the overactivation of MEK-ERK blocks the CXCL10 expression in cancer cells." (PMID 36429101, 2022).
cancer (continued). "This sequence flexibility will allow for the analysis of diverse types of NCVs, including somatic variants in cancer, rare variants found in population studies, or even synthetic variants as analyzed in our CXCL10 promoter analysis." (PMID 35252945, 2022). "Since it is an inflammatory chemokine, CXCL10 was associated with multiple disorders, including infectious diseases, autoimmune diseases, and cancer." (PMID 36366543, 2022). "Especially the high expression of genes encoding CX3CL1, CXCL9 and CXCL10 has been found in carcinomas highly infiltrated by effector TCs, particularly TH1, which show higher overall and disease-free survival." (PMID 35954497, 2022). "Originally, CXCL10 is shown to be proinflammatory and proliferative and is associated with advanced human cancer." (PMID 33681290, 2021). "Another cancer disease in which high levels of CXCL10 were associated with a good prognosis is epithelial ovarian carcinoma (HGSOC)." (PMID 34944943, 2021). "Given the relevance of type I interferon responses in cancer treatment, we wanted to evaluate its association with the Mø2:CXCL10 and T-cell:IFIT1 cell state colocalization signal in our spatial data." (PMID 34650042, 2021). "The most studied receptor of CXCL10 is CXCR3 (LR pair associated with immune response in 12 of the 18 cancer types), which is expressed by effector CD8+ T cells, T helper 1 cells, and NK cells, which are all antitumor lymphocytes." (PMID 34430923, 2021). "There are several studies suggesting that increased CXCL10 secretion in the TME is associated with cancer cell invasive properties and metastasis formation." (PMID 29690889, 2018). "We found induction of genes typical of influenza antiviral responses (CXCL10) as well as cancer associated genes upregulated in H1N1+ MG suggesting mammary glands." (PMID 26448646, 2015). "One of the three clusters contained eight genes, three of which have been implicated in cancer and cancer-related cellular phenotypes such as invasion, and included Cxcl10, Vil2 and Dnmbp." (PMID 18706093, 2008). "Furthermore, the oncoprotein LMP1 transforms fibroblasts into cancer‐associated fibroblasts (CAFs), which secrete cytokines and chemokines (including IL‐6, IL‐8, CXCL10, and TGF‐β) to alter cancer cell metabolism." (PMID 40365984, 2025). "Given the selective vulnerability of MTAP-deficient cancer cells to CB-839 treatment and the immunoregulatory role of CXCL10, we next evaluated whether glutaminase inhibition could enhance CXCL10 expression." (PMID 41246302, 2025). "Furthermore, the mechanism of oHSV induces TLS formation and remodels the TME was explored, including the association of CXCL10, and CXCR3 with the cancer patient's prognosis, as well as the impact of blocking CXCL10/CXCR3 pathway on TLS formation." (PMID 39219056, 2025). "CXCL10 is a potent chemoattractant produced in response to IFNγ stimulation that subsequently promotes T-cell trafficking to tumors and is associated with improved survival in multiple cancer types." (PMID 41463176, 2025). "Studies have shown that low expression of CXCL10 is associated with cancer development." (PMID 40805064, 2025). "What may explain the association between CXCL9 and CXCL10 expression and cancer prognosis, as well as the response to ICT?" (PMID 39474427, 2024). "In addition, the high levels of PD-L1 and CXCL10 were associated with a better overall survival rate in all cancer patients who received immunotherapies (n = 454)." (PMID 38953994, 2024). "Immunohistochemistry showed that three core proteins associated with the CXCR3 pathway, CXCR3, CXCL9, CXCL10, and were more highly expressed in cancer tissues from the immunotherapy-responder group than in tissues from the immunotherapy non-responder group (n = 1 per group)." (PMID 35562800, 2022). "Thus far most of the studies focused on the role of CXCL10 in cancer diseases, particularly associated with cancer prognosis." (PMID 34944943, 2021).
cancer (continued). "‎In the future, CXCL10 gene therapy could become a key component of ‎personalized cancer ‎treatment, ‎offering a novel approach to harness the immune system for ‎more effective cancer ‎therapies while ‎minimizing the risk of recurrence and metastasis." (PMID 40760734, 2025). "In addition, compared with untreated tumors, tumors treated with SGT-53 showed increased mRNA expression of chemokines including Cxcl9, Cxcl10, and Cxcl12, which are associated with increased infiltration of activated T cells in various human cancers via the chemokine receptors CXCR3 and CXCR4." (PMID 36359830, 2022). "In this context, co-culturing reovirus-infected bladder tumoroids with peripheral blood mononuclear cells was found to significantly enhance cancer death dose-dependently, alongside induction of key immune mediators such as CXCL10 and IFN-γ." (PMID 41631159, 2026). "For instance, the top-ranked common gene, C-X-C motif chemokine ligand 10 (CXCL10) is overexpressed in 30 cancer types, whereas chromogranin B (CHGB) expression is downregulated in 16 of the 31 TCGA solid cancers." (PMID 41567365, 2026). "In this respect, in the absence of TPR-specific CD8pos T cells, the treatment of OvCAR3 and PC3M cancer cells with EpCAM-ReTARGTPRIFNαR149A inhibits proliferation and stimulates cancer cell-secreted CXCL10 (IP-10)." (PMID 40243928, 2025). "CXCL10 is therefore an important player in cancer immunity, acting downstream of the JAK-STAT pathway to recruit immune cells, support Th1 responses and enhance immune surveillance." (PMID 40760734, 2025). "This dual action – improving immune cell function ‎while limiting angiogenesis ‎‎- underscores the significant potential of CXCL10 as a target in ‎cancer gene therapy." (PMID 40760734, 2025). "By ‎focusing on gene modulation, ‎personalized ‎strategies, and synergistic treatments, CXCL10 gene ‎therapy has the potential to ‎transform cancer ‎treatment." (PMID 40760734, 2025). "Upregulation of these genes was confirmed by qPCR, and ELISA demonstrated that secretion of CXCL9 and CXCL10 was strongly increased in cancer cells co-treated with TAK-243 and IFN-γ." (PMID 39540840, 2025). "In ESCC, for example, CXCL10 expression inhibits cancer cell invasion and promotes migration of immune cells to the cancer microenvironment, suggesting CXCL10 exerts an inhibitory effect on ESCC progression." (PMID 40029556, 2025). "Previous studies have shown that IRI triggers cancer recurrence through CXCL10/CXCR3 signaling to mobilize regulatory T cells." (PMID 40524699, 2025). "CXCL10 has emerged as a favorable prognostic biomarker for immunotherapy responsiveness across multiple cancer types." (PMID 41246302, 2025). "Early myeloid architecture dictates cancer fate: dense CXCL9+/CXCL10+ clusters with T-cell enrichment accompany regression, whereas sparse infiltration predicts progression." (PMID 41279770, 2025). "Pan-cancer analysis revealed that CD58 was associated with key immune regulatory factors, including PD-L1, chemokines (CCL5, CXCL9, CXCL10)." (PMID 41438981, 2025). "As a result, the CXCL10/CXCR3 pathway is a valuable target for the development of novel immunotherapeutic strategies in cancers such as GC." (PMID 41376630, 2025). "To identify novel pathways and drugs that regulate the IFNγ-dependent PD-L1, we expressed GFP under the control of mouse PD-L1 promoter in mouse cancer cells that up regulate PD-L1 and CXCL10 in response to IFNγ stimulation." (PMID 40264756, 2025). "In recent years, PARP inhibitors have been described to mediate the release of the two T-cell recruiting chemokines CCL5 and CXCL10 by activating the STING pathway in cancer cells." (PMID 40579444, 2025).
cancer (continued). "In HNC, CXCL10 expression has been positively correlated with overall survival, and studies in other cancers have identified CXCL10 as a positive prognostic factor for response to immunotherapy." (PMID 40149328, 2025). "In the present study, we observed both direct induction of apoptosis in TLR3-expressing cancer cells and strongly enhanced secretion of CXCL10 from cancer cells." (PMID 40029556, 2025). "To assess their function in cancer, we used Pf4creCx3cr1DTR mice, which predominantly deplete CD206hi IMs, including those that express Cxcl13 (for B cell chemotaxis), Cxcl9 and Cxcl10 (for NK and T cell recruitment), as well as Ccl6, Ccl8, Ccl9, and Ccl2418." (PMID 40630529, 2025). "This work focused on the molecular mechanisms by which these two drugs inhibit cancer cell growth, particularly through histone modifications to regulate the inflammatory genes CXCL10 and MECOM." (PMID 40805064, 2025). "This upregulation of ISGs upon ORMDL3 knockdown was consistent in the MC38 cancer model, where Ifnb1, Ccl5, and Cxcl10 mRNA levels were significantly elevated." (PMID 40126553, 2025). "CXCL10 signaling in immune and cancer cells activates multiple intracellular pathways that regulate cell survival, proliferation, and motility." (PMID 41516196, 2025). "Another cytokine of importance in carcinogenesis is the chemokine IP-10 (CXCL10), which is associated with chronic inflammation, immune dysfunction, and cancer development." (PMID 40733274, 2025). "BCAM-induced proteins, previously reported to drive EMT and associated processes such as cell migration in various cancers, include AREG, CXCL1, CXCL10, EDN1, FGF2, TGFβ1 and VEGFB." (PMID 40082910, 2025). "This review ‎aims to ‎provide an overview of the biological roles of CXCL10, its involvement in various ‎pathological ‎conditions, and its potential therapeutic applications in cancer." (PMID 40760734, 2025). "Through a wound healing assay and Transwell cell invasion assay, we demonstrated that the sulfated CXCR3-S2 peptide trap significantly reduced CXCL10-induced cancer cell migration and invasion." (PMID 38275412, 2024). "The Fc-wt ADCs potently induced CXCL10 production and cancer-cell killing activity with similar potency in both PBMC and monocyte co-cultures." (PMID 38992037, 2024). "Using NanoString gene expression technology, we analyzed tumors from mice treated with the VPS34 inhibitor SB02024 and demonstrated that the expression of CCL5 and CXCL10 is increased through a cGAS-STING-dependent mechanism within cancer cells." (PMID 40395527, 2024). "We first measured the expression of genes involved in adipocyte differentiation (PPAR-γ, AP2, HSL, Adiponectin, Leptin), cancer-associated fibroblast (CAF) markers (LIF, FAP, α-SMA), and inflammation (IL-6, IL-8, IL-1β, CXCL-10, TNF-α)." (PMID 39072314, 2024). "CXCL10 has been reported to have significant roles in various cancers when produced in high amounts." (PMID 39124881, 2024). "In our recent study, we explored the impact and underlying mechanisms of inhibiting the kinase activity of VPS34, a key lipid kinase in the autophagy/endosomal trafficking system, on the expression of CCL5 and CXCL10 in preclinical cancer mouse models." (PMID 40395527, 2024). "High expression of CXCL9 and CXCL10 has been strongly associated with improved survival and a substantial increase in the number of intratumoral CD8+ T cells in cancer patients treated with ICIs." (PMID 38434763, 2024). "CXCL9 is mainly produced by macrophages and DC, particularly CD106+ DC, whereas CXCL10 is mainly expressed by effector T cells and, in a wide range of tumors, by the cancer cells themselves." (PMID 39474427, 2024). "We also found that high PD-L1, ICAM1, and CXCL10 levels all correlated with better immunotherapeutic efficacy in patients with all cancers." (PMID 38953994, 2024).